IL6 (interleukin 6)
Diseases named in the same sentence as IL6 in open-access papers (continued):
Sharing a sentence is not in itself a finding about the gene and the disease.
tumor (continued). "Thus suggesting that tumor-derived IL-6 release is the main factor inducing GSH release form the liver." (PMID 23517603, 2013). "In addition, IL6 has pro-angiogenic properties, regulating immune cell infiltration, a stromal reaction, and the tumor-promoting actions of Th17 lymphocytes." (PMID 23889749, 2013). "Accordingly, we suggested that circulating IL-6 plays a role in tumor promotion, and the induction of angiogenesis and EMT might be the underling mechanisms." (PMID 23561329, 2013). "Serum IL-6 and IL-10 levels may serve as complementary tumor markers and contribute to the differential diagnosis in HCC patients." (PMID 27335826, 2013). "In addition, anticancer treatments, such as the chemotherapeutic agents doxorubicin or paclitaxel and radiation therapy, can also facilitate IL-6 release by tumor cells." (PMID 23517603, 2013). "Furthermore, serum IL-6 level was significantly decreased by the treatment with hochuekkito in tumor-bearing mice when compared to untreated mice." (PMID 23326296, 2012). "This may indicate IL-6 inhibits CXCL7 expression is one of the mechanism responsible for activating host immune system to against tumor." (PMID 23136963, 2012). "The different roles played by tumor-expressed IL6 in males and females need further investigation." (PMID 23185547, 2012). "IL-6 can either promote or inhibit the growth of tumor cells, depending on the cell type." (PMID 22523542, 2012). "IL-6 was highly expressed by cancer cells in tumor tissues from C26-bearing mice." (PMID 23326296, 2012). "Furthermore, hochuekkito treatment significantly reduced serum IL-6 level and IL-6 expression level in macrophages in tissues surrounding the tumor." (PMID 23326296, 2012). "Furthermore, pretreatment of H. pylori with the patient 1 soluble tumor mucins resulted in a gradual increase in production of both IL-6 and IL-8 with increasing mucin concentration by infected MKN7 cells." (PMID 22563496, 2012). "In addition to EGF, macrophages secrete multiple cytokines including TNF-α and IL-6 suggesting that macrophages in the tumor microenvironment are likely to initiate a signaling network that promotes tumor progression." (PMID 22529912, 2012). "Listeria monocytogenes could activate mitogen-activated protein kinases and nuclear factor-kappaB in tumor cells, resulting in the increased production of nitric oxide and interleukin-6 and enhanced proliferation of tumor cells." (PMID 22309608, 2012). "Inflammatory cytokines, including IL-1, IL-6 and IL-8, activate NF-κB pathways in tumor cells." (PMID 22567084, 2012). "The IL-6 and IL-8-dependent inflammatory network appears to significantly contribute to relating oncogene-induced cellular senescence with an inflammatory phenotype and tumor progression." (PMID 22848630, 2012). "In addition, IL-6 and IL-10 are promoters of two different immune response pathways, i.e. Th1 and Th2, and allow the evaluation of host immunological response to the tumour." (PMID 23181118, 2012). "In a mouse model of colitis-associated cancer (CAC), IKKβ was deleted in myeloid cells (leading to decreased NF-κB activity), tumor size was considerably smaller compared to controls and expression of pro-inflammatory cytokines, such as TNFα, IL-6, and IL-1, was also markedly reduced." (PMID 23284890, 2012). "Higher baseline plasma concentration of IL-6 correlated with larger baseline tumor size (p<0.05)." (PMID 22347360, 2012). "Furthermore, functionality of hyper-IL-6 in tumor-bearing mice resulted in elevated acute phase proteins (data not shown) as well as in accelerated epithelial barrier repair of tail lesions." (PMID 22236378, 2012). "Furthermore, IL-6 levels in tumor lysates from DIM treated mice were significantly less as compared to levels in the tumor lysates from control mice." (PMID 22280969, 2012). "IL-6 is produced by stromal cells like T-cells, fibroblasts or monocytes and also by tumor cells." (PMID 23145063, 2012).
tumor (continued). "Interleukin-6 (IL-6), a cytokine involved in tumor microenvironment control, was hypersecreted by MECs, and IL-6 exposure of NSCs resulted in the duplication of several responses in NSCs of conversion to CSCs via MEC co-culture (e.g., MMP hypersecretion, decreased PTEN)." (PMID 22472196, 2012). "For example, IL-6 is a growth and survival factor for many tumor types." (PMID 22870317, 2012). "It has been also reported that administration of an NF-κB inhibitor, dehydroxymethylepoxyquinomicin (DHMEQ), significantly decreased the serum IL-6 level in tumor-bearing cachectic mice, resulting in the improvement of both the epididymal fat weight and serum triglyceride level." (PMID 23326296, 2012). "This indicated active secretion of hyper-IL-6 by the infected tumor cells." (PMID 22236378, 2012). "IL-6 is also able to promote tumor angiogenesis and invasion." (PMID 22583829, 2012). "One of the events downstream of NF-κB activation is production of various cytokines and chemokines (e.g. IL-6, and IL-17) that attract leukocytes, which results in enhanced tumor progression, cancer cell growth and spread, angiogenesis, invasion and tumor immunosuppression." (PMID 22239913, 2012). "Quantitative RT-PCR analysis showed a significant increase in expression of IL-6 and IL-11 mRNA expression in tumour xenografts in SP-treated animals compared to the control group (2.7±0.2 fold, P<0.01 and 2.6±0.1 fold, P<0.05 for SP vs control for IL-6 and IL-11, respectively)." (PMID 22442729, 2012). "IL-6 is released in response to infection, burns, trauma, and neoplasia and can be produced by T lymphocytes, B lymphocytes, macrophages, endothelial cells, keratinocytes, and mesangial cells in normal tissues, as well as by hematologic neoplasms and human cancers." (PMID 23185547, 2012). "Tumor cells and other cells in the tumor microenvironment secrete cytokines such as IL-6, indolamine-2,3-dioxygenase, vascular endothelial growth factor, programmed death-1 ligand, and soluble Fas ligand, which hamper antitumor immunity and promote tumor growth." (PMID 24213505, 2012). "To evaluate this hypothesis we have measured the concentration of selected cytokines: TNF, IFNγ, IL-12 (p70), MCP-1, IL-6, and IL-10 in the tumor lysates and in the sera taken from mice at the time of their sacrifice." (PMID 23251384, 2012). "We also identified that a high IL6 expression in tumor cells was correlated with poor OS." (PMID 23185547, 2012). "Furthermore, IL-6 produced in epithelial cancer cells themselves plays an important role in tumor growth and metastasis, in an autocrine and/or paracrine manner." (PMID 21967801, 2011). "Therefore the elevation of IL-6 level in the circulation cannot be attributed to its production by tumor cells." (PMID 21760797, 2011). "Furthermore, α-TEA treatment modulated the tumor microenvironment in a proinflammatory fashion, as we found significantly higher IL-6 and CCL5 levels and a trend toward higher levels of other proinflammatory mediators (IL-1β, CCL2, CCL3, CCL4)." (PMID 21232138, 2011). "Because tumor cells produce various anti-inflammatory cytokines and growth factors, such as IL-6, IL-10, IL-13, VEGF, and M-CSF, OSCC-derived immunosuppressive cytokines may modulate infiltrating TAMs, leading to the M2 phenotype." (PMID 24213108, 2011). "IL-6 may also contribute to reprogram the tumor adjacent stromal microenvironment which may facilitate dissemination to the peritoneal cavity." (PMID 21619709, 2011). "In tissue culture and mouse models, non-specific inhibitors of the NFκB pathway like sodium salicylate or cyclopentenone prostaglandins can increase the sensitivity of Tax-tumor cells to apoptosis and repress NFκB-inducible cytokines IL-6, IL-10, IL-15, and IFN-γ." (PMID 21994759, 2011). "Furthermore, IL-6 mediated activation of STAT3 in tumor cells results in increases in anti-apoptotic, pro-proliferation, and pro-angiogenic genes." (PMID 22171994, 2011).
tumor (continued). "However, we did not observe high IL-6 levels within lymphocytes in the affected lymph nodes, rather high IL-6 levels were observed within the tumor epithelial cells which correlated with pStat3 levels (manuscript submitted, JFB)." (PMID 22140473, 2011). "While the role of IL-6 in the etiology of OC is not fully understood, we might predict that IL-6 contributes to OC by promoting angiogenesis, tumor invasion, and chemoresistance." (PMID 21765834, 2011). "Given that Gr-1+CD11b+ myeloid cells from tumor-bearing mice could inhibit T cell activation; we investigated if IL-6 induced Gr-1+CD11b+ myeloid cells can inhibit T cell function." (PMID 21394214, 2011). "The objective of this paper is to provide a brief consideration of ovarian surface epithelial-stromal interactions in regard to normal physiological function and tumor progression as influenced by two potentially key interleukins, interleukins-1 (IL-1) and -6 (IL-6), present in the microenvironment." (PMID 21765834, 2011). "Additionally, with increasing degrees of tumour invasion, the median levels of IL-6 evidenced a tendency to increase, and this difference in IL-6 levels was found to be statistically significant (P < 0.001)." (PMID 21294915, 2011). "Tumor progression is characterized by the involvement of cytokines and growth factors and Twist induction has been connected with a number of these signaling pathways including IL-6." (PMID 21559372, 2011). "IL-6 is released by the peritoneal mesothelial cells and concentrates in ascites where it could affect tumor cell behaviour." (PMID 21619709, 2011). "As tumor sphere formation and tumor cell aggressiveness are correlated and IL-6 in tumor cells triggers malignant features in tumor spheres, we evaluated whether TG2 and downstream IL-6 were involved in tumor-sphere formation in vitro." (PMID 21967801, 2011). "Alternatively, IL-6 could stimulate the proliferation of tumor cells leading to a shorter progression-free survival." (PMID 21619709, 2011). "Since blockade of IL-6 signaling by shRNA inhibits lung adenocarinoma cell growth, IL-6RA treatment may inhibit radiation-induced lung toxicity as well as tumor proliferation." (PMID 20374625, 2010). "Pro-inflammatory effects of Il6 have been shown in several tumor cell lines." (PMID 20628605, 2010). "Cachexia induced by the C26 tumor appears to depend on elevated interleukin (IL)-6 plasma levels." (PMID 21048967, 2010). "Of note, most genes in this signature gene set are not reported direct targets of IL-6 or genes that are implicated in tumor cell growth or survival." (PMID 21179572, 2010). "Furthermore, we have characterized phenotypic changes in response to enforced expression of IL-6 in tumor growth and resistance to chemotherapy." (PMID 21179572, 2010). "In the supernatants of untreated NK cells co-cultured with UCLA-OSCCs, synergistic induction of GM-CSF, IL-6 and IL-8 could be observed since much lower levels of these cytokines were induced either in the presence of NK cells alone or tumor cells alone." (PMID 20661281, 2010). "Findings from other research did not reveal a significant association between IL-6 and tumor stage, or other clinical findings." (PMID 20465852, 2010). "The tumour cells secrete the cytokines IL-23 (99%) and IL-6 (99%)." (PMID 20877351, 2010). "For these studies, we performed analysis in Mz-ChA-1 cells that were stably transfected with full-length IL-6 and which results in elevated basal IL-6 production, promotion of cell survival and resistance to chemotherapy and enhancement of tumor cell xenograft growth in vivo." (PMID 21179572, 2010). "Presence of micrometastatic tumor cells in liver may induce the kupffer cells to produce a variety of cytokines (IL-Ib, IL-6 ve TNF), which may modulate albumin synthesis by hepatocytes." (PMID 21176210, 2010).
tumor (continued). "Similar tumor promoting effects were reported for coinjection of fibroblasts or fibroblast conditioned medium with tumor epithelial cells supporting a role for soluble factors such as IL-6." (PMID 20509882, 2010). "Thus, excessive Stat3 activity enforces differentiation into Th17 cells even in the context of Th1 polarising anti-tumour conditions, and genetic interference with the IL6/gp130 pathway selectively blocks Th17 cell polarization." (PMID 20478049, 2010). "In order to determine whether the 3-D environment is required for sustained IL-6 expression by epithelial cells we cultured tumor cells (either from MCF10A-Ras xenografts or MMTV-Ras tumors) and passaged them on plastic dishes (2-D environment)." (PMID 20929542, 2010). "However, the authors of that study found significant correlation between large tumor size and hepatic metastasis correlated with elevated IL-6 levels significantly." (PMID 20465852, 2010). "Another question is whether other parameters such as inflammatory cytokines (e.g. IL-1β, IL-6, IL-8), placental growth factor or circulating tumour cells should have been explored to gain better insight in pharmacodynamic alterations at the tumoural level." (PMID 20823884, 2010). "Our data indicate that both CCL3 and IL-6 are produced at high levels by tumor-associated DCs (not shown), which is supported by independent reports." (PMID 21113407, 2010). "A reduction in rate of tumor growth was seen in Mz-ChA-1 and Mz-IL-6 xenografts with both agents." (PMID 21179572, 2010). "However, what effects our combination therapy has on expression levels of such cytokines as IL-6 in the serum of tumor bearing mice in our model remains to be determined." (PMID 19956757, 2009). "Similarly, LNCaP/IL-6 tumour in nude mice rapidly regressed after castration; however, LNCaP/Co tumour growth was transiently inhibited after castration and then continuously accelerated." (PMID 19844233, 2009). "Interestingly, increases in serum IL-6 levels in sunitinib-treated animals correlated with increases in tumor size, suggesting different mechanisms for the cytokine aberrations seen between selective versus broad spectrum anti-VEGF strategies." (PMID 19888452, 2009). "The biological basis for this paraneoplastic phenomenon may be similar to other paraneoplastic processes in which there is the elaboration of interleukin-6 (IL-6) as well as growth factors produced by the tumor." (PMID 19126192, 2009). "While several growth factors may be necessary for the in vivo progression of the Skov-3 tumor, in vitro studies revealed huMSC-induced IL-6 secretion to be critical for the enhanced proliferation observed in Skov-3/MSC TGA." (PMID 19352430, 2009). "However, low levels of IL-6 in the sera of sunitinib-treated animals correlated with tumor progression." (PMID 19888452, 2009). "Furthermore, MSC-conditioned medium stripped of IL-6 induced the same growth rates observed in the Skov-3 tumor cells alone." (PMID 19352430, 2009). "Additionally, with increasing degrees of tumor invasion, the median levels of IL-6 evidenced a tendency to increase, and this difference in IL-6 levels was found to be statistically significant (P < 0.001)." (PMID 19457231, 2009). "Although our data showed no positive correlation between serum IL-6 and CRP levels, elevation of the CRP level is primarily determined by an increase of circulating IL-6, and the IL-6 level is correlated with the serum CRP level as well as with tumor histological grade and metastasis." (PMID 19656379, 2009). "Circulating interleukin-6 can be considered a promising tumor marker for HCC." (PMID 27942274, 2009). "NBEC expressed IL-12R and released constitutively tumor promoting cytokines (e.g. IL-6 and CCL2)." (PMID 19582164, 2009).
tumor (continued). "Alternatively, among primary tumor cells able to produce relatively low amounts of IL-6, only few cells metastasize hematogenously into bone marrow cavities where the IL-6 gene is reactivated to produce a high level of IL-6 in order to survive successfully." (PMID 19497133, 2009). "Therefore, it is expected that the accumulation of IL-6 is much higher in the environment of the primary tumours than in the environment of the metastases." (PMID 18728665, 2008). "We then hypothesised that the high accumulation of IL-6 may have downregulated Mage-b-specific immune responses at the site of the primary tumour." (PMID 18728665, 2008). "Effectiveness of IL-6 in this respect may depend on the quantity of basal and inducible IL-6 expressed as the tumour progresses through stages of malignancy." (PMID 18205904, 2008). "We therefore have evaluated the effect of IL-6 modulators, i.e. IL-1β, prostaglandin E2, 17β-estradiol, and 1,25-dihydroxyvitamin D3, on expression and synthesis of the cytokine at different stages of tumour progression." (PMID 18205904, 2008). "Furthermore, it has previously been demonstrated that monocytes maintain IL-6 secretion throughout their differentiation to macrophages when continuously stimulated with HNSCC tumour spheroids in vitro." (PMID 18234094, 2008). "In fact MFH cells secrete high levels of IL-6 and elevation of the IL-6 occurs on tumor recurrence." (PMID 19025608, 2008). "Whether IL-6 has contributed to T-cell inhibition at the site of the primary tumour in vivo needs to be further analysed." (PMID 18728665, 2008). "These patients may have an immune reaction to the neoplasm, as elevated levels of interleukin-6 and elevated levels of antimyocardial antibodies have been described." (PMID 18706121, 2008). "This suggests that the tumour itself, its supporting vasculature and/or stroma may be the source of IL-6." (PMID 18059400, 2008). "If unopposed, massive release of IL-6 under the stimulation by IL-1β might accelerate tumour progression to high stage malignancy by paracrine proliferative action on IL-6-responsive, i.e., still differentiated cells." (PMID 18205904, 2008). "In previous studies, we found that 4T1 primary tumours produced high levels of IL-6." (PMID 18728665, 2008). "Moreover, IL-6 and TGF-β1 plasma levels measured during follow-up were significantly associated with the individual tumour responses of these patients." (PMID 18682839, 2008). "Furthermore, our data indicate a significant association between the IL-6 and TGF-β1 plasma levels and the individual tumour responses assessed at the same time-points during follow-up." (PMID 18682839, 2008). "However, IL-6 is highly abundant in undifferentiated tumour cells and is effectively stimulated by IL-1β." (PMID 18205904, 2008). "While we may be able to credit the antiproliferative effects of IL-6 signalling for enhancing tumour control, broader effects on the inflammatory response may well also be involved." (PMID 17987036, 2007). "Based on the in vitro results, we hypothesised that the combination of IL-6 and sIL-6Rα is present in the tumour milieu and facilitates IL-6 trans-signalling, which in turn has consequences for tumour survival and proliferation." (PMID 17987036, 2007). "To test this hypothesis, we determined whether IL-6 trans-signalling influences the in vivo tumour response to PDT." (PMID 17987036, 2007). "We hypothesise that IL-6 trans-signalling can compensate in part for PDT-induced loss of signalling through the membrane-bound IL-6Rα, thus providing IL-6 responsiveness in the post-PDT tumour environment." (PMID 17987036, 2007). "We have reported earlier that PDT can abolish cellular responsiveness to cytokines and growth factors, including IL-6, through the loss of their respective membrane receptors, which would render the abundantly present IL-6 in the tumour environment ineffective." (PMID 17987036, 2007).